MALAT1 (metastasis associated lung adenocarcinoma transcript 1)
Diseases named in the same sentence as MALAT1 in open-access papers (continued):
Sharing a sentence is not in itself a finding about the gene and the disease.
Obesity (continued). "Recent studies point toward the possible regulatory roles of two lncRNAs; metastasis-associated lung adenocarcinoma transcript 1 (MALAT1) and taurine upregulated gene 1 (TUG1) in the pathogenesis of obesity-related disorders and regulation of lipogenesis and adipogenesis." (PMID 32368256, 2020). "We next tested the hypothesis that, akin to our results in old mice, Malat1 expression levels in WAT are also reduced in conditions of obesity." (PMID 29746487, 2018). "It is also plausible that challenges/conditions other than aging and diet-induced obesity could best highlight the physiological and molecular actions of Malat1." (PMID 29746487, 2018). "Therefore, in an attempt to realize the molecules involved in the pathogenesis of obesity, here, we aimed to evaluate the expression of MALAT1 and TUG1, as well as plausible target genes (PPARγ, PGC1α, SREBP-1c, FAS, and ACC), in VAT and SAT from obese women compared to normal-weight subjects." (PMID 32368256, 2020). "Although to the best of the authors’ knowledge, this study was one of the first to draw attention to the possible role of MALAT1 and TUG1 in the pathogenesis of obesity in humans, some limitations of the current study deserve to be mentioned." (PMID 32368256, 2020). "In contrast with the present results, MALAT1 was seen to be significantly down-regulated in SAT from both genetic and diet-induced models of obesity." (PMID 32368256, 2020). "Reductions in Malat1 expression in subcutaneous WAT (scWAT) were also observed in genetic (ob and db) as well as diet-induced models of obesity." (PMID 29746487, 2018). "Despite our endeavors to understand the roles of lncRNAs MALAT1 and TUG1 in the context of metabolic disorders, the precise role of these lncRNAs in obesity and to understand how they interact with dietary factors remain unclear." (PMID 38167433, 2024). "However, the transcription levels of MALAT1 and TUG1 showed a positive correlation with major lipogenic and adipogenic genes, and thus the authors suggested possible roles of MALAT1 and TUG1 in obesity." (PMID 38674413, 2024). "It is noteworthy that in old female mice as well as in models of obesity, Malat1 expression was downregulated in scWAT rather than in vWAT." (PMID 29746487, 2018). "More importantly, MALAT1 and TUG1 transcript levels showed positive correlations with master lipogenic and adipogenic genes which might be indicative of the possible role of MALAT1 and TUG1 in obesity possibly through regulating the lipogenic and adipogenic genes." (PMID 32368256, 2020). "Thus, energy balance was not impacted by the absence of Malat1 in the settings of diet-induced obesity." (PMID 29746487, 2018). "However, contrary to our hypothesis, engineered genetic deletion of Malat1 in mice did not influence fat gain or glucose tolerance upon aging (at least until 8 months old) nor in the context of diet-induced obesity." (PMID 29746487, 2018). "Therefore, we conclude that the overall metabolic impact of the absence of Malat1 on adipose tissue accretion and glucose intolerance is either physiologically not relevant upon aging and obesity, or that it is masked by as yet unknown compensatory mechanisms." (PMID 29746487, 2018). "Therefore, in light of the present findings, we conclude that the overall metabolic impact of the absence of Malat1 on adipose tissue accretion and glucose intolerance is either physiologically not relevant upon aging and obesity, or that it is masked by as yet unknown compensatory mechanisms." (PMID 29746487, 2018).
pulmonary fibrosis (15 papers, 2014 to 2022). Chronic progressive interstitial lung disorder characterized by the replacement of the lung tissue by connective tissue, leading to progressive dyspnea, respiratory failure, or right heart failure. "Overall, Malat1 causes a change in the microenvironment by triggering macrophage activation to control lung fibrosis." (PMID 33533071, 2021). "One lncRNA, namely Malat1, is reported to control pulmonary fibrosis in association with macrophage activation." (PMID 33533071, 2021). "Moreover, MALAT1 is upregulated in pulmonary fibrosis caused by silica exposure." (PMID 36419933, 2022). "Knocking out MALAT1 reduced LPS-induced systemic and pulmonary inflammation and injury, but more severe bleomycin-induced pulmonary fibrosis and M2 alveolar macrophage augmentation were observed in mice." (PMID 36685535, 2022). "Eventually, MALAT1 deficiency abrogates EMT via targeting the miR-503-mediated PI3K/AKT/mTOR/Snail pathway, which can repress silica-induced pulmonary fibrosis." (PMID 36186445, 2022). "For instance, MALAT1‐mediated M1 polarization is involved in different pulmonary processes and plays opposite roles in lung injury and pulmonary fibrosis." (PMID 36685535, 2022). "Malat1 knockout ameliorated LPS-induced pulmonary inflammation and injury but led to severe lung fibrosis." (PMID 36685535, 2022). "In this regard, in amodel of silica induced pulmonary fibrosis, MALAT-1 acts as a ceRNA for miR-503, one of whose targets is PI3K p85." (PMID 29701689, 2018). "Taken together, our data suggested that MALAT1-miR-503-PI3K/Akt/mTOR/Snail pathway plays critical roles in silica-induced pulmonary fibrosis." (PMID 28900284, 2017). "MALAT1 deletion promotes glucose-derived mitochondrial oxidative phosphorylation (OxPhos) to boost both M2 polarization and profibrotic differentiation of macrophages, which leads to the progression of bleomycin-induced pulmonary fibrosis in mice." (PMID 36186445, 2022). "MALAT1 is a key gene involved in the regulation of lung fibrosis." (PMID 36419933, 2022). "We then examined whether lncRNA MALAT1 is correlated with the process of EMT in silica-induced pulmonary fibrosis." (PMID 28900284, 2017). "In contrary, in mouse model of pulmonary fibrosis induced by silica, miR-503 was reduced in fibrotic lung tissue and cells exposed to silica compared with control, but long non-coding RNA MALAT1 was upregulated, and MALAT1 regulated miR-503 expression by competitively binding to miR-503." (PMID 33762949, 2021). "Furthermore, MALAT1 also play an important role in EMT related to the pulmonary fibrosis." (PMID 32596346, 2020). "MALAT1 and lnc-ATB can stimulate the EMT process by competitively binding miR-503 and miR-200c and then promote silica-induced pulmonary fibrosis." (PMID 35444701, 2022). "It concentrated on the EMT-suppressive effects of miR-503 on the silica-induced pulmonary fibrosis via the classical PI3K/Akt/Snail signaling pathway, and the lncRNA MALAT1 serves as a molecular sponge to competitively decrease the expression of miR-503." (PMID 28900284, 2017). "In pulmonary fibrosis, there is a negative correlation between MALAT1 and miR-503 expression that can inhibit pulmonary fibrosis." (PMID 36419933, 2022). "Hence, MALAT1 positively regulates E2F1 expression through the cyclin D1-CDK4-Rb signaling axis, exerts EMT effects, and promotes the development of pulmonary fibrosis." (PMID 36419933, 2022). "Consequently, lncRNA MALAT1 could induce the onset of EMT and promote the process of lung fibrosis by adsorbing miR-145." (PMID 36494831, 2022). "Furthermore, in a silica particle-induced lung fibrosis mouse model, lncRNA MALAT1, as a molecular “sponge”, could adsorb miR-503, reduce the expression of miR-503, and activate the PI3K/Akt/Snail signaling pathway, leading to EMT and triggering lung fibrosis." (PMID 36494831, 2022).
preeclampsia (14 papers, 2017 to 2024). Preeclampsia is a hypertensive disorder of pregnancy that is characterized by new-onset hypertension with proteinuria presenting after 20 weeks of gestation, and depending on mild or severe forms may initially present with severe headache, visual disturbances, and hyperreflexia. "Expression levels of PFKFB3 and metastasis-associated lung adenocarcinoma transcript-1 (MALAT1) are reduced in placental tissues of early-onset preeclampsia patients." (PMID 39318551, 2024). "Our results showed that decreased MALAT1 expression weakened the proliferation, invasion, and migration ability of trophoblasts, which was similar with studies in preeclampsia and recurrent spontaneous abortion." (PMID 39199376, 2024). "According to research, lncRNA MALAT1 levels in plasma exosomes from pregnant women with Preeclampsia were positively correlated with vascular endothelial growth factor (VEGF) expression levels." (PMID 37745705, 2023). "We also previously demonstrated the role of the MALAT1/miR-26/PFKFB3 axis in the pathogenesis of early-onset preeclampsia (EOPE) and proposed that targeting PFKFB3 to drive glycolysis is a promising therapeutic strategy for EOPE." (PMID 36354563, 2022). "MALAT-1 down-regulation was described to impair proliferation, cell cycle, apoptosis, and migration of trophoblast cells involved in the preeclampsia." (PMID 28553318, 2017). "This suggests that downregulating lncRNA MALAT1 levels in plasma exosomes may speed up the progression of Preeclampsia by controlling VEGF expression, which in turn suppresses angiogenesis." (PMID 37745705, 2023). "As noncoding RNAs are an important part of evolutionary genetics and have been confirmed to play regulatory roles in preeclampsia, seven lncRNAs reported to be associated with hypoxia were selected, including UCA1, EFNA3, H19, MALAT1, HOTAIR, FALEC, and HAS2-AS1." (PMID 36160709, 2022). "Among them, lncRNA MALAT1 may be involved in the pathogenesis of preeclampsia via the regulation of the proliferation, cell cycle, apoptosis, migration and invasion of trophoblast cells." (PMID 33085209, 2020). "MALAT-1 downregulation in preeclampsia could therefore have a huge impact on placentation and further development of the placenta over the course of gestation." (PMID 31212604, 2019). "Knocking down MALAT1 can inhibit the expression of PFKFB3, thereby reducing glycolytic activity and ultimately leading to abnormal angiogenesis in early-onset preeclampsia." (PMID 39318551, 2024). "Collectively, the MALAT1/miR-26/PFKFB3 axis regulates EC angiogenesis by regulating glycolysis and plays a key role in the pathogenesis of early-onset preeclampsia." (PMID 39318551, 2024). "The deregulation of lncRNAs IGF2/H19, MEG3, SPRY4‐IT1, HOTAIR, MALAT1, FLT1P1 and CEACAMP8 in placental trophoblasts is involved in the pathogenesis of preeclampsia." (PMID 33085209, 2020). "Combining with H19, MALAT-1, MEG3 and so on, the involvement of lncRNAs in preeclampsia will become more clear." (PMID 32194641, 2020). "Several lncRNAs, including MALAT1, HOXA11-AS and MEG3, had been demonstrated to be involved in the dysfunction of trophoblasts in RM diseases and pathogenesis of preeclampsia." (PMID 31572567, 2019).
coronary artery disease (13 papers, 2019 to 2025). "In a study conducted in a medical setting, it has been found that the lncRNA referred to as lnc-MALAT1 is linked to a higher likelihood of developing coronary artery disease (CAD) and a larger size of stenosis in the coronary arteries." (PMID 39171328, 2024). "The latest studies have shown that MALAT1 expression levels are significantly greater in patients with coronary artery disease (CAD) and T2DM, and can be used as a better diagnostic indicator for CAD." (PMID 38439031, 2024). "The lncRNA MALAT1 (metastasis-associated lung adenocarcinoma transcript 1), on the other hand, has reduced expression in patients with coronary artery disease." (PMID 31682178, 2019). "Vitamin D deficiency has been linked to elevated MALAT1 expression in patients with coronary heart disease, and vitamin D intake may be associated with modulation of this inflammatory lncRNA's expression in those patients." (PMID 36653874, 2023). "Vitamin D deficiency has been linked to increased MALAT1 expression in patients with coronary heart disease, and vitamin D intake may be associated with modulation of the expression of this inflammatory lncRNA in those patients." (PMID 36653874, 2023). "In vascular endothelial cells, the differential expression of MALAT1 is associated with several cardiovascular diseases, and MALAT1 is associated with the inflammation and apoptosis of vascular endothelial cells, risk of coronary heart disease, and deep vein thrombosis." (PMID 37109540, 2023). "In contrast, prior investigations have established a link between HOTAIR and MALAT1 with coronary artery disease and heart failure." (PMID 39172906, 2024). "Moreover, expression of MALAT1 is affected by vitamin D status in patients with coronary artery disease and healthy subjects." (PMID 38475720, 2024). "For example, lncRNA NEAT, miR-130a, miR-30a, lncRNA MALAT1, and mitochondrial lncRNA LIPCAR were elevated in the peripheral blood of patients with coronary heart disease such as AMI and MIRI." (PMID 35370737, 2022).
endometrial cancer (13 papers, 2020 to 2025). Primary or metastatic malignant neoplasm involving the endometrium (mucous membrane that lines the endometrial cavity). "In contrast, MALAT1 is down-regulated in Endometrial Cancer, is associated with poor prognosis, and is a tumor protective factor." (PMID 35600372, 2022). "The present study provides evidence that MALAT1 rs664589 C>G significantly increased the risk of endometrial cancer." (PMID 31880028, 2020). "The MALAT1 rs664589 C>G polymorphism was associated with a significant increase in endometrial cancer risk." (PMID 31880028, 2020). "We genotyped three MALAT1 polymorphisms in 249 endometrial cancer cases and 446 cancer‐free female controls using quantitative polymerase chain reaction with TaqMan probes." (PMID 31880028, 2020). "We investigated the association with endometrial cancer of each of the three selected MALAT1 polymorphisms." (PMID 31880028, 2020). "We further explored the association of MALAT1 rs664589 C>G polymorphisms with endometrial cancer susceptibility by stratified analysis." (PMID 31880028, 2020). "Fourth, although our findings suggested that MALAT1 rs664589 C>G significantly increased the risk of endometrial cancer, more studies are needed to confirm this result and determine potential mechanisms and functions in the future." (PMID 31880028, 2020). "Although the current case‐control study provided evidence that the common MALAT1 polymorphisms are associated with the risk of endometrial cancer susceptibility in Southern Chinese women, several limitations should be addressed." (PMID 31880028, 2020). "First, only three common MALAT1 polymorphisms were genotyped in the current study; hence, additional common MALAT1 polymorphisms should be investigated to fully illuminate the contribution of polymorphisms in MALAT1 to endometrial cancer susceptibility." (PMID 31880028, 2020). "Subsequently, relative expression levels of MYST4 and MALAT1 in eight gynecological cancer cell lines, including six OC lines and two endometrial cancer cell lines, were evaluated by a real-time PCR analysis normalized to HTB75 expression." (PMID 34638541, 2021). "As for endometrial cancer, miR-200c-3p has been reported to be increased in EC tissue and could cooperate with lncRNA MALAT1, a classical long coding RNA related to endometrial tumorigenesis." (PMID 34368370, 2021). "Zhao et al20 analyzed MALAT1 expression in endometrial cancer in 2014." (PMID 31880028, 2020). "Stratified analysis further demonstrated that the MALAT1 rs664589 C>G polymorphism significantly increased the risk of endometrial cancer susceptibility in patients with no history of surgery, more deliveries, BMI between 25 and 29.9, and FIGO stages II‐III." (PMID 31880028, 2020). "In addition, targeting the MALAT1/miRNA-200c-3p axis in a xenograft endometrial carcinoma model strongly inhibited tumour growth." (PMID 32993558, 2020). "However, the roles of MALAT1 polymorphisms in the etiology of endometrial cancer have not been well documented." (PMID 31880028, 2020). "MALAT1 4102217 C>G association with endometrial cancer risk was not discovered in our study." (PMID 31880028, 2020). "In endometroid endometrial cancer cells with re-expressed PCDH10, transcription of the Wnt target gene MALAT1 was suppressed." (PMID 35468745, 2022). "LncRNAs that play a role in tumor suppression in endometrial cancer include: FER1L4, GAS5, MEG3, RP11-395G23.3, LA16C −313D11.11, Xist, Linc ROR, MALAT1, HOTAIR, OVAL, SRA, etc., However, the mechanism of cuproptosis-associated LncRNAs in endometrial cancer is still unclear." (PMID 37124623, 2023). "Besides HOTAIR, a subset of lncRNAs including H9, MALAT1, and GAS5 have been proven to have an anomalous level in EC patient tissue, affecting the occurrence, development, and metabolism of endometrial cancer through different mechanisms." (PMID 34368370, 2021).
viral infection (13 papers, 2020 to 2025). "Notably, viral-infection-induced downregulation of MALAT1 expression has been associated with enhanced activation of IRF3 and production of type I IFNs, suggesting its antiviral role in therapy." (PMID 39940816, 2025). "MALAT1 has been implicated in immune regulation, including modulating pro-inflammatory cytokine production and activating T cells and natural killer cells upon bacterial or viral infections." (PMID 37325561, 2023). "Generally, viral infections result in reduced expression of Malat1, promoting antiviral IFN production." (PMID 38693436, 2024). "In this context, metastasis associated lung adenocarcinoma transcript 1 (MALAT1) and nuclear paraspeckle assembly transcript 1 (NEAT1) are two lncRNAs implicated in neurodegenerative process and viral infection, also in association with TDP-43." (PMID 36675095, 2023). "In line with this research, the gene expression of MALAT1 was upregulated by virus infection in normal human bronchial epithelial (NHBE) cells." (PMID 35807375, 2022). "MALAT1 seems to be more involved in viral infection, such as HPV, enterovirus type 71, flavivirus, and SARS-CoV-2." (PMID 35335994, 2022). "It is known that lncRNA Malat1 can inhibit the production of type I IFN in macrophages after virus infection, and lncRNA Sros1 can promote IFN-γ–STAT1 mediated innate immunity." (PMID 33766129, 2021). "In fact, expression of Malat1 is decreased upon viral infection but is increased upon stimulation with TLR ligands such as LPS and poly(I:C)." (PMID 34582376, 2021). "Among them, lncRNA MALAT1 has recently been recognized as an essential regulator involved in cancer development, innate immunity, and viral infection." (PMID 34240756, 2021). "Emerging research has highlighted yet another role for MALAT1 lncRNA in viral infection and innate immune processes, affirming the crucial roles it plays in many biological processes." (PMID 32646047, 2020). "The altered expression of MALAT1 was found both in viral infection and sepsis." (PMID 35335994, 2022). "Malat1 upregulation in certain viral infections may contribute to a protracted immune response." (PMID 38693436, 2024). "However, Malat1 function may increase in certain viral infections, such as HIV, Coxsackie myocarditis or mild COVID-19." (PMID 38693436, 2024). "Whereas the downregulation of lncRNA PVT1 seems to protect pancreatic β cells from injury, both up-regulated MALAT1 and NEAT1 had been related to inflammatory mediators (TNF-alpha, IL-6, CXCL10), SLE pathogenesis and innate immune response against viral infections." (PMID 35058920, 2021). "As expected, the PA-X-deficient virus did not cause significant downregulation of ACTB and G6PD transcripts compared to mock-infected cells, and the decrease in POLR2A and MALAT1 transcript was weaker although not significantly different from the WT virus infection." (PMID 38629840, 2024).